INS (insulin)
Diseases named in the same sentence as INS in open-access papers (continued):
Sharing a sentence is not in itself a finding about the gene and the disease.
Hyperglycemia (continued). "The situation is different in hyperglycemia; in the beta cell, hyperglycemia closes K ATP channels, the depolarization eliciting the release of insulin, the release of GABA being essentially a resting release, nothing much changes." (PMID 22954255, 2012). "Gestational diabetes also exposes the fetus to hyperglycemia, which stimulates an increase in fetal insulin and an increased rate of fetal fat storage." (PMID 22988897, 2012). "Exercise training for 8 weeks was effective in ameliorating insulin sensitivity even though the magnitude of reduction in hyperglycemia was small (9% of reduction)." (PMID 23285277, 2012). "DM is a syndrome characterized by abnormal insulin secretion, derangement in carbohydrate and lipid metabolism, and it is diagnosed by the presence of hyperglycemia." (PMID 23843827, 2012). "Hyperglycemia developed within hours after the surgery, but it was matched by the inhibition of the insulin response to glucose." (PMID 22747890, 2012). "The results also suggest that the reduced intracellular insulin content in chronic hyperglycemia are partially due to the decrease in insulin gene transcription." (PMID 22509362, 2012). "Management of hyperglycemia by chemical drugs or insulin involves various drawbacks such as that induced by sulfonyl ureas and chronic anorexia nervosa, brain atrophy and fatty liver induced by insulin." (PMID 22899998, 2012). "A prolonged increase in the demand for insulin often leads to defects in insulin secretion, resulting in sustained hyperglycemia." (PMID 22474424, 2012). "In the current study, the experimental hyperglycemia condition increased insulin secretion and intravenous glucose loading omitted the effect of glucose on gut increments; otherwise, these hormones augment GIIS and potentiate the peripheral insulin effects." (PMID 23493150, 2012). "Late pregnancy is catabolic and characterised by increasing insulin resistance, lipolysis, hyperinsulinaemia, hyperglycaemia, increased postprandial fatty acid concentrations, and declining maternal fat reserves." (PMID 22675354, 2012). "Such risk factors include the use of insulin in pregnancy, high BMI, recurrent GDM, higher glucose levels in oral glucose tolerance testing, and fasting hyperglycaemia during pregnancy." (PMID 22577574, 2012). "Type 2 Maturity Onset Diabetes of the Young (MODY2) is a monogenic autosomal disease characterized by a primary defect in insulin secretion and hyperglycemia." (PMID 22761713, 2012). "Similar to our previous report, correction of hyperglycemia by insulin or phlorizin reverses this higher expression of cTnI in STZ rats." (PMID 21702924, 2011). "Initiation of insulin therapy is still being delayed by approximately 9 years, resulting in many Asian patients developing severe hyperglycemia." (PMID 21631903, 2011). "In fact, hyperglycemia induces the glycation of insulin in pancreatic β cells and glycated insulin is unable to regulate glucose homeostasis in vivo and to stimulate glucose transport and adipose tissue lipogenesis." (PMID 21819598, 2011). "After improvement of fasting hyperglycaemia with basal insulin therapy, much of the remaining glycaemic exposure is due to postprandial excursions." (PMID 21679291, 2011). "In the insulin resistant condition, postprandial glucose output from the liver is often uninhibited, contributing to hyperglycemia." (PMID 21886789, 2011). "Currently, as recommended by ACE/ADA, insulin is the most appropriate agent for management of hyperglycemia." (PMID 20811546, 2011). "Zone D represents children with hyperglycemia and insulin resistance; zone H represents children with hyperglycemia and β-cell dysfunction." (PMID 21276273, 2011). "While the treatment and management of hyperglycemia especially in T2D has always been based on insulin response, emerging evidence suggests that inhibition of glucagon signalling presents a potential approach to the maintenance of normal glucose levels." (PMID 22046328, 2011).
Hyperglycemia (continued). "Palmitoleic acid reduced body weight increase, ameliorated the development of hyperglycemia and hypertriglyceridemia, and improved insulin sensitivity." (PMID 21774832, 2011). "Despite the recent questioning of the intensity of insulin treatment of critical illness hyperglycemia, in a clinical perspective the effects of insulin on muscle protein metabolism should be considered and further investigated." (PMID 21483870, 2011). "Overexpression of the β-cell specific miRNA, miR-375, in pancreatic islets reduce insulin secretion and reduced β-cell mass was detected in the miR-375 knock-out mouse as well as hyperglycaemia." (PMID 22216196, 2011). "In a study performed in 6 Pima Indians with T2D, the BA pool was found to be increased during untreated hyperglycaemia and conversely decreased upon insulin therapy." (PMID 21736725, 2011). "Studies in human subjects found that administration of ghrelin induces hyperglycaemia and reduces insulin secretion, probably through a direct glycogenolytic effect." (PMID 21760816, 2011). "The massive destruction of pancreatic beta cells after STZ injection is due to alkylation of DNA thereby producing hyperglycaemia, and it accounts for drastic reduction in insulin level which in turn alters glucose utilization and metabolism." (PMID 20953435, 2011). "It is a metabolic disorder marked by high blood sugar level (hyperglycemia), occurs when pancreas cannot produce enough of insulin (type 1 DM) or body cannot effectively use the produced insulin (type 2 DM)." (PMID 22389848, 2011). "Surprisingly, there have been very few studies describing glucose control in PN patients with hyperglycemia treated with insulin provided in the PN mixture." (PMID 20811546, 2011). "Although the initial levels of serum insulin and C-peptide were low in our case, hyperglycemia resolved in three days by thiamine treatment only." (PMID 21448333, 2011). "Nine (53%) patients developed prolonged hyperglycaemia and six (35%) were treated with insulin (with mean BG level of 2.7 g/L (1.9 to 3.0))." (PMID 21612615, 2011). "This occurred during a restaging scan for cervical cancer following administration of insulin in the setting of measured hyperglycemia." (PMID 22214514, 2011). "Nonetheless, once diagnosed patients with T1D receive exogenous insulin to reduce they hyperglycemia." (PMID 21304603, 2011). "Early stages of the disease are characterized by resistance of the liver and peripheral tissues to insulin signal, resulting in hyperglycemia, hyperinsulinemia, and glucose intolerance." (PMID 21592922, 2011). "A bilberry extract added to the diet (10 g anthocyanins/kg diet) of male KK-Aγ mice (a type 2 diabetic model) for 5 weeks ameliorated hyperglycemia and increased insulin sensitivity compared to control animals." (PMID 21569436, 2011). "Cani and co-workers also showed that oligosaccharide administration lowered glucose-stimulated insulin secretion, improved glucose tolerance, reduced hyperglycemia, and insulin-sensitive hepatic glucose production in high-fat-fed diabetic mice." (PMID 22205091, 2011). "Hyperglycemia resulting from defection in insulin action or insulin production leads to a number of complications." (PMID 21716679, 2011). "In an insulin-resistant state, impaired insulin action promotes hepatic glucose production and reduces the uptake of glucose by peripheral tissues, resulting in systemic hyperglycemia." (PMID 22102892, 2011). "In the long run, hyperglycemia diminishes insulin action through “toxic” effects on insulin sensitive tissues." (PMID 21603181, 2011). "In fat-induced diabetic mice treated daily with F-FTS, both the incidence of hyperglycemia and the levels of serum insulin were significantly decreased." (PMID 21738773, 2011). "A careful adaptation of the insulin dose is mandatory in order to avoid corticosteroid-induced hyperglycaemia." (PMID 22145998, 2011).
Hyperglycemia (continued). "Type 1 diabetes results from autoimmune and/or inflammatry processes that selectively disrupt insulin-producing pancreatic β-cell, and is characterized by hyperglycemia due to reduced insulin secretion." (PMID 20924496, 2011). "One possibility is the participation of insulin, particularly since this hormone was shown to be relevant for the dopaminergic response to hyperglycemia." (PMID 21980372, 2011). "This between- and within-subject variability in pharmacological action, which in turn results in unpredictable effects with hypoglycaemia and hyperglycaemia, is particularly problematic with human insulin preparations." (PMID 21410860, 2011). "Beta-cell function was measured as the insulin response to hyperglycaemia, arginine and GLP-1 stimulation." (PMID 21406078, 2011). "Hyperglycemia elicits the secretion of insulin by the pancreas; the ensuing hiperinsulinemia tries to counter the muscle insulin resistance." (PMID 22029632, 2011). "This study was designed to investigate the modulating effects of OPE on hyperglycemia and insulin-insensitivity in HFD/STZ-induced diabetic rats." (PMID 21439094, 2011). "Type 2 DM is a complex, multisystem disease with a pathophysiology that includes a defect in insulin secretion, increased hepatic glucose production, and resistance to the action of insulin, all of which contribute to the development of overt hyperglycemia." (PMID 21791087, 2011). "It was suggested that hyperglycaemia impairs glucose and insulin regulation of NO production which occur through AMP-activated protein kinase." (PMID 21235803, 2011). "AdipoR1 and AdipioR2 can be regulated under physiological and pathophysiological states, such as fasting, insulin, hyperglycemia." (PMID 21912612, 2011). "T2DM is characterized by chronic abnormal high blood glucose levels (hyperglycemia), insulin resistance, and a relative insulin secretion defect." (PMID 21350721, 2011). "It is likely, therefore, that the effects of palmitoleic acid on hyperglycemia and hypertriglyceridemia can be attributed to improved insulin sensitivity." (PMID 21774832, 2011). "While a reduction in endogenous insulin production precipitates the onset of hyperglycemia, it is commonly stated that the onset of hyperglycemia occurs when 80–95% of an individual's beta cells are destroyed." (PMID 22073210, 2011). "These cells displayed regulated insulin secretion in response to various secretagogues in vitro, while clusters of these clones were able to reverse hyperglycaemia induced by streptozotocin in mice." (PMID 21716654, 2011). "The restoration of pro-survival pathways by phloridzin treatment along with the partial effect of subconjunctival insulin administration on the same pathways suggest retinal growth factor resistance due, at least in part, to systemic hyperglycemia." (PMID 22046295, 2011). "Selective loss of GSK-3β in skeletal muscle improves glucose tolerance and insulin signaling, while removal of this isoform in β-islet cells can reduce hyperglycaemia in diabetic IRS-2 KO mice." (PMID 21253590, 2011). "Cumulatively, these events lead to hyperinsulinemia and hyperglycemia due to impaired insulin-mediated regulation of glucose levels." (PMID 21569551, 2011). "Despite the higher insulin concentration, glucose level was approximately 3-times higher in HFD rats indicating a state of hyperglycemia and insulin resistance." (PMID 21829658, 2011). "One of the significant concerns of the use of diazoxide and other agents to decrease insulin secretion is the potential to lead to significant side effects including gastrointestinal disturbances, biliary gallstones, edema, and hyperglycemia." (PMID 21603206, 2011). "Lines of evidence have demonstrated that EA is capable of improving hyperglycemia in the fasting stage, with a marked increase in plasma insulin levels in diabetic rats." (PMID 20981161, 2011).
Hyperglycemia (continued). "Transient insulin treatment optimized by continuous subcutaneous insulin infusion (CSII) is effective in rapidly reducing hyperglycemia and glucotoxicity, and leads to the restoration of insulin sensitivity in T2DM." (PMID 22046277, 2011). "Management of hyperglycemia and insulin dosing in patients receiving parenteral nutrition should be done on an individual basis, regardless of indication." (PMID 20811546, 2011). "Purified cyanidin 3-glucoside (2 g/kg diet for 5 weeks) ameliorated hyperglycemia and increased insulin sensitivity in diabetic mice." (PMID 21569436, 2011). "Diabetes mellitus is one of the most common endocrine metabolic disorders, characterized by hyperglycemia due to defects in insulin secretion, action, or both." (PMID 22116046, 2011). "The objective of this study was to investigate the occurrence of hyperglycemia and insulin response in critically ill children with meningococcal disease in the intensive care unit of an academic children's hospital." (PMID 21276273, 2011). "We postulated that controlling post-meal hyperglycaemia with a prandial + basal insulin regimen can attenuate meal-induced increases of these inflammatory cytokines." (PMID 21517955, 2011). "Since the two treatments have different effects on hyperglycemia and insulin levels, they were then used in combination to test for a potential additive effect." (PMID 22046295, 2011). "Several studies have investigated the specific roles of insulin and hyperglycemia using similar approaches to study their impact on brain metabolism." (PMID 22046295, 2011). "In summary, our study shows that controlling post-meal hyperglycaemia with prandial + basal insulin attenuates the meal-induced increases in hsCRP, TNF-α and interleukin-6 compared with basal insulin once daily, both plus metformin." (PMID 21517955, 2011). "Islets formed in vitro secrete insulin in response to the glucose concentration, and improve hyperglycemia when transplanted in the kidney capsules of hyperglycemic mice." (PMID 22145030, 2011). "Numerous clinical trials have demonstrated the efficacy of TZDs to reduce hyperglycemia and HbA1c levels, and improve insulin sensitivity." (PMID 20936101, 2010). "The leaves of insulin plant (Costus igeus) reduced the fasting and postprandial blood sugar levels, bringing them down towards normal, in dexamethasone-induced hyperglycemia in rats." (PMID 20814523, 2010). "The only mouse in these groups that developed late hyperglycemia showed pancreatic insulitis and reduction in β-islet insulin secretion (bottom rows)." (PMID 20625402, 2010). "It is also important that patients are aware that infection generally exacerbates hyperglycaemia and, thus, they should monitor their glucose levels and continue to take insulin as appropriate, even if their caloric consumption is reduced." (PMID 20456170, 2010). "It is possible that in hyperglycemia cancer cells are inherently better at responding to the effects of insulin compared to insulin-resistant “normal” cells." (PMID 20182531, 2010). "Invitro rodent models have shown MSC derived from BM and spleen with capability of insulin-secretion to treat hyperglycemia." (PMID 21197448, 2010). "Elevated insulin levels arise as a result of persistent hyperglycemia and peripheral insulin resistance." (PMID 20182531, 2010). "Maternal hyperglycemia leads to foetal hyperglycaemia, stimulating the foetal pancreas to synthesize excessive insulin." (PMID 21138582, 2010). "Regarding glycemic control, T2DM patients with elevated raised AD ratio qualify for more proactive approaches to control hyperglycemia with insulin-sensitizers and/or insulin replacement therapy." (PMID 21156040, 2010). "The primary task of prandial insulin is to suppress hepatic glucose production and stimulate utilisation of glucose by muscle, thus preventing hyperglycaemia after meals." (PMID 20618882, 2010).
Hyperglycemia (continued). "Treatment of diabetic GK rats with IL-1ra attenuates hyperglycemia, reduces the proinsulin/insulin ratio, and improves insulin sensitivity." (PMID 21113299, 2010). "Metformin ameliorates hyperglycemia by decreasing hepatic glucose output and gastrointestinal glucose absorption and improving insulin sensitivity, and is often the first drug used to treat newly diagnosed T2D in the United States." (PMID 20936101, 2010). "Only after further study in clinical trials should such devices be used to assist in titrating insulin during hyperglycemia management in critical care settings." (PMID 20925914, 2010). "When a fetus (over 12th week of gestation) is exposed to high levels of maternal glucose, it responds by secreting high levels of insulin in its circulation to control these hyperglycemias." (PMID 21052542, 2010). "While this is true in a normal cellular environment, in hyperglycemia there is a limit on substrate availability because of insulin resistance." (PMID 20182531, 2010). "The amount of insulin administered to maintain that level of hyperglycemia also seemed different between strains." (PMID 20806092, 2010). "The first studies with ghrelin showed that acute ghrelin treatment induced hyperglycemia and reduced insulin secretion in healthy humans during the first hours of treatment." (PMID 20700401, 2010). "In this study, we aim to establish an animal model to monitor insulin gene expression in extrapanceatic tissues in vivo and characterize the time-course of the insulin promoter activation in liver induced by hyperglycemia through bioluminescence imaging (BLI)." (PMID 20195523, 2010). "Mortality was higher in very preterm infants with hyperglycemia treated with insulin during the neonatal period." (PMID 20646308, 2010). "Hyperglycemia produced by glucose injections in mice led to the appearance of proinsulin- and insulin-positive cells in the liver within 3 days." (PMID 20195523, 2010). "Until 12 months of age, progressive rising values of fasting hyperglycemia and glucose intolerance are accompanied by higher levels of circulating insulin indicating resistance to the hormone." (PMID 20236525, 2010). "The decrease in mortality reported in the 2001 Leuven trial after intensive insulin therapy led to a considerable change in clinical practice, with hyperglycemia in ICU patients becoming less acceptable." (PMID 20840773, 2010). "As β-cell function continues to decline, insufficient insulin is secreted to control blood glucose adequately and chronic fasting and/or postprandial hyperglycaemia becomes established." (PMID 20089006, 2010). "Experiments suggest that mild hyperglycemia leads to increased expression of the functioning glucokinase gene, thus limiting the severity of the defect in glucose-stimulated insulin secretion." (PMID 20587063, 2010). "A possible explanation for these results is the upregulation of the transcription factor early growth response protein 1 (Egr-1), which in turn downregulates TRAIL expression in endothelial cells, by both hyperglycemia and insulin." (PMID 20634940, 2010). "Metformin (MET) lowers hyperglycemia by reducing hepatic gluconeogenesis in the presence of insulin and improving insulin sensitivity by increasing peripheral glucose uptake and utilization." (PMID 20804556, 2010). "An inevitable complicating factor in this study was the concomitant occurrence of hyperglycemia and insulin therapy, through which the individual influence of hyperglycemia or insulin therapy cannot be demonstrated." (PMID 20646308, 2010). "Although beta-cell proliferation and blood insulin levels are increased a long time after Men1 is excised in beta cells, little is known as to whether Men1 excision within a short time can prevent development of hyperglycemia in diabetes mouse models and its underlying mechanisms." (PMID 21318185, 2010). "Maternal hyperglycemia leads to excess fetal insulin, which in turn acts as a growth hormone for the fetus." (PMID 21159203, 2010).